CTSL (cathepsin L)
Diseases named in the same sentence as CTSL in open-access papers (continued):
Sharing a sentence is not in itself a finding about the gene and the disease.
Hypertension (6 papers, 2021 to 2024). The presence of chronic increased pressure in the systemic arterial system. "The development of hypertension involves extensive arterial wall remodeling, in which CTSL plays an essential role." (PMID 38555403, 2024). "Using an angiotensin II-induced hypertension model, researchers observed an increase in blood pressure and CTSL activity." (PMID 39150053, 2024). "Interestingly, our study revealed a strong correlation between CTSL activity and concentration with hypertension and CHD in these patients." (PMID 39150053, 2024). "In addition to being correlated with severity, CTSL was also positively correlated with age and history of hypertension but was negatively correlated with CTSB." (PMID 33774649, 2021). "ACE2, ADAM17, and CTSL all showed a clear trend of joint upregulation in healthy tissues compared with DCM, ICM, and hypertension." (PMID 37259108, 2023).
pancreatic cancer (6 papers, 2012 to 2024). "Recently, a specific cathepsin inhibitor, ASPER-29, was found to suppress pancreatic cancer cell metastasis through dual inhibition of cathepsin-L and cathepsin-S." (PMID 39595046, 2024). "Our data and reports from literature support these findings indicating that KRAS-mutant pancreatic cancer cells harbor significant cathepsin L activity." (PMID 34070180, 2021). "Top expressing tissues were similar on gene and protein levels for ACE2 (colorectal, kidney, pancreas, and stomach), TMPRSS2 (prostate and pancreatic cancers), and CTSL (renal and skin cancers)." (PMID 33633121, 2021). "Immunohistochemical analyses of pancreatic cancer tissues revealed that expressions of cathepsin B and cathepsin L are indicators of a poor prognosis." (PMID 22792318, 2012). "In addition, it has been reported in the literature that CTSL is highly expressed in the plasma of patients with pancreatic cancer and can be used as an independent predictor of pancreatic cancer." (PMID 31632196, 2019). "Inhibition of cathepsin L achieved in this work is of particular importance for pancreatic cancer treatment, where cathepsin L is considered to be an independent prognostic marker, and its inhibition could be used to reduce cancer invasion and tumor growth, and merits further investigations in vivo." (PMID 35539052, 2019).
cardiac hypertrophy (5 papers, 2013 to 2021). "Cathepsin L overexpression was reported to improve cardiac function, inflammation, and fibrosis in models of cardiac hypertrophy, and its deficiency in mice results in progressive dilated cardiomyopathy." (PMID 34575910, 2021). "Consistently, cathepsin L-deficient mice subjected to aortic banding showed exaggerated cardiac hypertrophy compared to sham animals." (PMID 29576856, 2018). "In conclusion, mice with CTSL deficiency demonstrated an accelerated response to pathological stress resulting in exacerbated cardiac hypertrophy and dysfunction." (PMID 23608608, 2013). "Phenylephrine‐induced cardiac hypertrophy in vitro was more pronounced in CTSL‐deficient neonatal cardiomyocytes than in in controls." (PMID 23608608, 2013). "In the in vivo murine model of aortic banding (AB), a deficiency in CTSL markedly exacerbated cardiac hypertrophy, worsened cardiac function, and increased mortality." (PMID 23608608, 2013). "In this study, CTSB and CTSL were found to be downregulated in cardiac hypertrophy, potentially implying slightly limited myocardial proteolytic activity." (PMID 32176724, 2020). "Cathepsin L, a lysosomal enzyme, has been shown to play an important role in protecting myocardium via activation of autophagy in cardiac hypertrophy." (PMID 29576856, 2018). "Lysosomal CTSL attenuates cardiac hypertrophy and preserves cardiac function through facilitation of autophagy and proteasomal protein processing." (PMID 23608608, 2013). "In age-matched groups, cardiac CTSD was significantly downregulated in SCH (p = 0.006) and CTSL was moderately downregulated in CCH (p = 0.021); however, p62, ATPSC, and ASNC were not upregulated in cardiac hypertrophy." (PMID 32176724, 2020).
emphysema (5 papers, 2011 to 2025). "Cathepsin L has a key role in phagocytosis and intracellular protein degradation; this can be related to both pulmonary emphysema development and the impaired alveolar macrophages functions reported in COPD." (PMID 40243422, 2025). "This study identified a distinct eosinophil phenotype in emphysematous mouse lungs, revealing the critical role of eosinophil-derived cathepsin L (CTSL) in the development of emphysema." (PMID 37816708, 2023). "Further investigations are warranted to explore therapeutic strategies targeting cathepsin L in emphysema patients." (PMID 37816708, 2023). "Mechanistic studies utilizing CTSL inhibitors and an eosinophil-deficient mouse model verified the role of CTSL in ECM degradation and emphysema development." (PMID 37816708, 2023). "RNA-seq analysis demonstrated that CTSL was highly expressed in eosinophils derived from patients with emphysema and asthma-COPD overlap." (PMID 37816708, 2023). "A particularly noteworthy discovery is that eosinophil-derived cathepsin L contributed to the degradation of the extracellular matrix, thereby leading to emphysema in pulmonary tissue." (PMID 37816708, 2023). "Collectively, these findings underscore the significant role of eosinophil-derived cathepsin L in extracellular matrix degradation and remodeling, and its relevance to emphysema in COPD patients." (PMID 37816708, 2023). "Increased levels of cathepsin L have been observed in BALF of patients with emphysema, and alveolar macrophages from COPD patient secrete more cysteine protease than macrophages from smokers without disease, or those from non-smokers." (PMID 21915293, 2011). "Moreover, Macro_SPP1 cells showed elevated expression of protease genes (e.g., ADAM9, CTSL, CTSS, and MMP9) in COPD, which were associated with emphysema and airway remodeling." (PMID 40589761, 2025). "The transition in CTSL dynamics was akin to that of eosinophils during emphysema development." (PMID 37816708, 2023). "Additionally, adenoviral gene delivery using AAV-CTSL substantially downregulated CTSL levels and emphysema severity in the lungs compared with the control group." (PMID 37816708, 2023). "Inhibition of cathepsin L resulted in a reduction of elastase-induced emphysema in a mouse model." (PMID 37816708, 2023). "Additionally, the elastolytic ability of eosinophils isolated from the emphysema models was limited by the CTSL inhibitor." (PMID 37816708, 2023). "This study underscores the potential of CTSL as a therapeutic target in emphysema patients." (PMID 37816708, 2023). "In addition, CTSL expression in eosinophils was positively correlated with emphysema in COPD patients." (PMID 37816708, 2023). "Therefore, CTSL is a potential therapeutic target in emphysema patients, especially those with eosinophilia." (PMID 37816708, 2023). "Consequently, targeting eosinophil-derived cathepsin L could potentially offer a therapeutic avenue for emphysema patients." (PMID 37816708, 2023). "Eosinophil-derived CTSL is crucial for ECM degradation and remodeling, resulting in emphysema development." (PMID 37816708, 2023). "Importantly, eosinophil levels correlated positively with serum cathepsin L levels, which were higher in emphysema patients than those without emphysema." (PMID 37816708, 2023). "CTSL was predominantly enhanced in eosinophils but not in neutrophils in emphysema models." (PMID 37816708, 2023). "Moreover, patients with emphysema had increased serum CTSL and CTSS levels compared to patients lacking emphysema (P < 0.001 for CTSL, P = 0.0046 for CTSS)." (PMID 37816708, 2023).
head and neck squamous cell carcinoma (5 papers, 2022 to 2025). A squamous cell carcinoma that arises from any of the following anatomic sites: lip and oral cavity, nasal cavity, paranasal sinuses, pharynx, larynx, and salivary glands. "In addition, CTSL was negatively correlated with both OS and DFS in LUAD, LUSC, LGG, and GBM and negatively correlated with DFS in head and neck squamous-cell carcinoma and PRAD." (PMID 35155389, 2022).
triple-negative breast carcinoma (5 papers, 2022 to 2025). An invasive breast carcinoma which is negative for expression of estrogen receptor (ER), progesterone receptor (PR), and human epidermal growth factor receptor 2 (HER2). "The authors further confirmed the nuclear localisation of CtsL in triple negative breast cancer patients, confirming a negative correlation between the levels of nuclear CtsL and TP53BP1, further reinforcing the nuclear activity of CtsL." (PMID 39851495, 2025).
autoimmune disease (4 papers, 2010 to 2024). A disorder resulting from loss of function or tissue destruction of an organ or multiple organs, arising from humoral or cellular immune responses of the individual to their own tissue constituents. "This implies that lysosomal proteases such as cathepsin L and S play a critical role in each step of pathogenesis for autoimmune diseases via complex molecular mechanisms." (PMID 20877570, 2010). "Interestingly, T-cells from patients with autoimmune diseases exhibit CTSL-dependent complement hyper-activation and IFNγ production." (PMID 38542346, 2024). "CTSL drives the differentiation of CD4+ T cells into T-helper-17 cells, and this effect was suppressed by a small CTSL-selective inhibitor, suggesting that targeting the CTSL regulatory module could be an approach to the management of Th17 cell-driven autoimmune disorders." (PMID 37202785, 2023).
colitis (4 papers, 2014 to 2025). Inflammation of the colon. "Heparanase was shown to stimulate macrophage activation, which in colitis induces production (i.e., via TNFα) and activation (via cathepsin L) of latent heparanase in the colon epithelium, together generating a vicious cycle that powers colitis and the associated tumorigenesis." (PMID 24465803, 2014). "Collectively, these data suggest a role for cathepsin S, and possibly cathepsin L, in promoting colitis symptoms." (PMID 41436824, 2025). "Zhenhu Zhang’s study demonstrated significantly higher expression levels of CTSL in ESCC tissues than adjacent non-cancerous tissues; Shengnan Zhao’s research revealed increased cathepsin B levels in colonic tissue and exacerbated dextran sodium sulfate (DSS)-induced colitis." (PMID 39359476, 2024).
influenza (4 papers, 2016 to 2022). An acute viral infection of the respiratory tract, occurring in isolated cases, in epidemics, or in pandemics; it is caused by serologically different strains of viruses (influenzaviruses) designated A, B, and C, has a 3-day incubation period, and usually lasts for 3 to 10 days. "Overall, these results suggest a critical role for CTSL in containing airway influenza A infection in mice, in which influenza causes enduring structural changes to alveoli and small airways." (PMID 27716790, 2016). "One such inhibitor, amantadine, a licensed anti-influenza drug, was shown to significantly inhibit CTSL activity after SARS-CoV-2 pseudovirus infection by suppressing transcription of the CTSL-encoding gene to prevent SARS-CoV-2 infection both in vitro and in vivo." (PMID 35682877, 2022). "Furthermore, we showed that amantadine, a licensed anti-influenza drug, significantly inhibited CTSL activity after SARS-CoV-2 pseudovirus infection and prevented infection both in vitro and in vivo." (PMID 33774649, 2021). "Furthermore, amantadine, a licensed anti-influenza drug, significantly inhibited CTSL activity after SARS-CoV-2 pseudovirus infection and prevented infection both in vitro and in vivo." (PMID 33774649, 2021). "This hypothesis predicts that influenza will be more severe in mice lacking CTSL." (PMID 27716790, 2016).
Insulin resistance (4 papers, 2020 to 2025). Increased resistance towards insulin, that is, diminished effectiveness of insulin in reducing blood glucose levels. "Impaired Cathepsin L expression in the skeletal muscle is associated with Type 2 Diabetes and insulin resistance both in animals and humans." (PMID 33922918, 2021). "Therefore, the observed decrease in Cathepsin L in skeletal muscle, a tissue already at high risk for androgen-mediated insulin resistance, is more likely a consequence of the insulin resistance that characterizes our PCOS model." (PMID 33922918, 2021).
liver fibrosis (4 papers, 2011 to 2025). "Elevated CTSL, a pro-inflammatory protease associated with liver fibrosis, was also found in both human AH and Fpr2−/− EtOH mice." (PMID 39337294, 2024). "Cathepsin L also plays a critical role in the pathogenesis of hepatic fibrosis since it can proteolytically degrade components of the extracellular matrix (ECM) whose accumulation in liver tissue alters the hepatic structure leading to cirrhosis." (PMID 36674470, 2023). "However, the role of decreased CTSL expression in inducing angiogenesis during liver fibrosis is yet to be established experimentally." (PMID 21687683, 2011).
osteoporosis (4 papers, 2019 to 2024). A condition of reduced bone mass, with decreased cortical thickness and a decrease in the number and size of the trabeculae of cancellous bone (but normal chemical composition), resulting in increased fracture incidence. "CTSL-knockout mice show increased resistance to osteoporosis following ovariectomy." (PMID 35881476, 2022).
Parkinson disease (4 papers, 2021 to 2025). A progressive degenerative disorder of the central nervous system characterized by loss of dopamine producing neurons in the substantia nigra and the presence of Lewy bodies in the substantia nigra and locus coeruleus. "As cathepsin L is associated with neurological problems such as Parkinson’s disease, urological issues such as proteinuria and even cancers, it would be of great relevance to study the intervention of maquicystatins in these disorders." (PMID 37239031, 2023). "Furthermore, genetic variants, reduced protein levels, and diminished catalytic activity of CTSB and CTSL have been associated with neuropathology, including Parkinson’s disease, highlighting the essential role of both proteases in maintaining neuronal health." (PMID 40883786, 2025). "Moreover, treadmill training has been shown to upregulate lysosomal proteins (LAMP2 and cathepsin L) in Parkinson’s disease, implying that treadmill training increased the activities of the lysosome to fuse with the autophagosome and destroy dysfunctional mitochondria in neural cells." (PMID 34440215, 2021).
Pick disease (4 papers, 2015 to 2024). A rare neurodegenerative disorder leading to dementia. "In particular, cathepsin L has been previously implicated in the proteolytic processing of progranulin, suggesting its potential role in the pathogenesis of frontotemporal dementia." (PMID 38329128, 2024). "Besides, Cathepsin L is considered as a key intracellular lysosomal protease and provides a link between lysosomal dysfunction and frontotemporal lobar degeneration." (PMID 34462639, 2021). "The gene Niemann-Pick disease, type C2 (NPC2) is upregulated in early disease and is connected to cathepsins L and B (CTSL, CTSB) and GLB1 in the lung network." (PMID 28330499, 2017). "Cathepsin L (CTSL), which primes the filovirus glycoprotein in the endosome, EXT1, which is involved in biosynthesis of heparan sulfate, and Niemann-Pick disease, type C1 (NPC1), showed strong bias against MARV entry." (PMID 26596270, 2015).
reovirus infection (4 papers, 2015 to 2026). "These hits include SLC35A1 and CTSL, whose gene products are required for reovirus infection." (PMID 35320319, 2022). "Following reovirus infection, IFN-β mRNA levels significantly decreased, by more than 75% in the presence of either cathepsin B inhibitor or cathepsin L inhibitor in the tumor cells, regardless of susceptibility to reovirus." (PMID 25866783, 2015).
Sepsis (4 papers, 2019 to 2024). Sepsis is defined as life-threatening organ dysfunction caused by a dysregulated host response to infection. "The pathogenic mechanisms of bacterial infections and resultant sepsis are partly attributed to dysregulated inflammatory responses sustained by some late-acting mediators including the procathepsin-L (pCTS-L)." (PMID 38550581, 2024). "The pathogenesis of microbial infections and sepsis is partly attributable to dysregulated innate immune responses propagated by late-acting proinflammatory mediators such as procathepsin L (pCTS-L)." (PMID 37239992, 2023). "Here, we report that the expression and secretion of procathepsin-L (pCTS-L) was induced by serum amyloid A (SAA) in innate immune cells, contributing to its late and systemic accumulation in experimental and clinical sepsis." (PMID 36735789, 2023). "Cathepsin L activity was increased in RV by PAB, while sepsis inhibited this response." (PMID 31247004, 2019).
skin cancer (4 papers, 2012 to 2021). "Transfer of cathepsin L-deficient bone marrow into the K14-HPV16 mouse model of skin cancer did also not affect cancer progression." (PMID 22798952, 2012). "Cathepsin L-ablated mice showed increased carcinogenesis and frequency of lymph node metastasis in K14-HPV16 skin cancer mice." (PMID 22798952, 2012).
acute myeloid leukemia (3 papers, 2021 to 2024). Acute myeloid leukemia (AML) is a group of neoplasms arising from precursor cells committed to the myeloid cell-line differentiation. "Cathepsin L, an endolysosomal cysteine protease, increases its activity in peripheral blood mononuclear cells (PBMNCs) and bone marrow mononuclear cells (BMMNCs) of patients with acute myeloid leukemia (AML)." (PMID 38881758, 2024).
Alzheimer disease (3 papers, 2022 to 2025). A progressive, neurodegenerative disease characterized by loss of function and death of nerve cells in several areas of the brain leading to loss of cognitive function such as memory and language. "Interestingly, several cathepsins, including CTSB, CTSD and CTSL have been implicated in the pathogenesis not only of PD, but also additional neurodegenerative disorders including Alzheimers Disease (AD)." (PMID 39587654, 2024). "Multiple studies on Alzheimer’s disease pathology demonstrated anti-amyloidogenic properties of CTSB or CTSL via direct or indirect enhancement of its enzymatic activity." (PMID 40883786, 2025).
bladder cancer (3 papers, 2021 to 2025). "Recent studies have revealed a close association between CTSL and bladder cancer." (PMID 40226717, 2024). "Studies have proposed CTSL as an independent predictor of bladder cancer and invasiveness in patients with a history of urothelial carcinoma." (PMID 34885040, 2021). "CTSL promoter activity and synthesis is driven by tumor secreted cytokines, and its upregulation is reported in a wide range of malignancies, including bladder cancer." (PMID 34885040, 2021).
breast tumor (3 papers, 2015 to 2024). "Of the total of 373 breast tumors that were successfully analyzed for cathepsin L, 298 (80%) showed a high (TIS 6–12) and 75 (20%) a low (TIS 0–5) expression." (PMID 39331316, 2024). "Consistent with the in vitro experiments, analysis of human breast tumor samples identified cathepsin L as a biomarker which inversely correlates with 53BP1." (PMID 26157794, 2015).
coronary heart disease (3 papers, 2024). "Importantly, serum levels of cathepsin L are elevated among patients with coronary heart disease and the cardiac release of cathepsin L is associated with apoptosis." (PMID 38862712, 2024). "In addition, another study showed that high expression of CTSL induced increased spontaneous apoptosis in monocyte-derived macrophages in patients with coronary artery disease." (PMID 38672131, 2024).